LELP1 (late cornified envelope like proline rich 1)
Tractability: No criterion of Open Targets' tractability assessment is met for any kind of drug.
Gene: Protein-coding gene on chromosome 1 (153,203,430 to 153,205,120, forward strand). Ensembl gene ENSG00000203784.
Pathways (Reactome):
Developmental Biology: Formation of the cornified envelope
Gene Ontology:
Molecular function: protein binding
Genetic constraint (gnomAD): Loss-of-function variants: 2 observed, 1.05 expected, observed/expected ratio (o/e) 1.9, 90% interval 0.51 to 1.94. That is too few expected variants to judge how well the gene tolerates losing a copy. Missense variants: 122 observed, 125.23 expected, observed/expected ratio (o/e) 0.97, 90% interval 0.84 to 1.13. Synonymous variants: 57 observed, 48.74 expected, observed/expected ratio (o/e) 1.17, 90% interval 0.94 to 1.46.
Homologues: Orthologues: pig LELP1 (67% identical), mouse Lelp1 (57% identical). Paralogues in human: KPLCE (32% identical), LCE5A (29% identical), LCE2B (28% identical), LCE2D (28% identical), LCE1E (27% identical), LCE1F (27% identical), LCE2C (27% identical), LCE2A (26% identical), LCE1D (22% identical), LCE3D (21% identical), LCE3B (20% identical), LCE3E (20% identical), and 8 more.